JAK2 (Janus kinase 2)
Diseases named in the same sentence as JAK2 in open-access papers (continued):
Sharing a sentence is not in itself a finding about the gene and the disease.
COVID-19 (70 papers, 2020 to 2025). A disease caused by infection with severe acute respiratory syndrome coronavirus 2. "To validate our framework, we first applied it to four clinically relevant drug–target pairs associated with COVID-19: Nirmatrelvir–MPro, Remdesivir–RdRp, Baricitinib–JAK2, and Dexamethasone–glucocorticoid receptor." (PMID 40871562, 2025). "We also tested JAK-2 and lymphocyte percentage, both as causal consequence of BMI and as causes of COVID-19 severity." (PMID 41359762, 2025). "Due to the non-involvement of JAK2 in type I or type II interferon-related cell signaling, selective JAK2 inhibitors are the preferred treatment choice for suppressing IL-6-GM-CSF-signaling-in COVID-19-associated cytokine storms." (PMID 37021053, 2023). "By searching for DTGs associated with IRGs shared between COVID-19 and IS, we identified eight DEGs interacting with two known databases of drug targets: JAK2, ORM1, RNASE2, TNFSF13B, CYBB, EIF2AK2, CD79B and CAMP." (PMID 36969251, 2023). "Proof of concept was demonstrated with the JAK1/JAK2 inhibitor baricitinib, which improved recovery time among patients with COVID-19–associated pneumonia when added to remdesivir." (PMID 36226977, 2022). "Ruxolitinib is under clinical investigation to evaluate COVID-19-associated lung injury, and another JAK2 inhibitor, nintedanib, is being evaluated for SARS-CoV-2-induced pulmonary fibrosis." (PMID 34067609, 2021). "It has been recently proposed that JAK2 inhibitor (Fedratinib@) can prevent the deteriorating outcomes of TH17 associated cytokine storm in COVID-19 by suppressing the production of several TH17 signature cytokines." (PMID 33762960, 2021). "Gain-of-function mutations like JAK2 V617 F result in constitutive activation of the pathway and may exacerbate hyperinflammatory responses, thereby worsening COVID-19 pathology." (PMID 40410684, 2025). "Moreover, since JAK2 appears to be not involved in type I or type II interferon-signaling, selective Jak-2 specific inhibitors may provide a better outcome for suppressing IL-6-GM-CSF-signaling-in COVID-19-associated cytokine storms." (PMID 40410684, 2025). "However, JAK-2 was suggested as mediating the signalling pathway of inflammatory cytokines (i.e.: IL 6) and anti-JAK-2 inhibitors are suggested for use to mitigate SARs-CoV-2 infection." (PMID 41359762, 2025). "Baricitinib, a selective and reversible inhibitor of the Janus kinases JAK1 and JAK2, previously approved for the treatment of rheumatoid arthritis, has been recently licensed for the treatment of severe Coronavirus disease 2019 (COVID-19) (COVID-19 Treatment Guidelines Panel." (PMID 36140425, 2022). "We investigated the effect of BMI on leptin, JAK2 and lymphocyte percentage and their effect on COVID-19 severity." (PMID 41359762, 2025). "Functionally, relevant mutations and polymorphisms in JAK family proteins, including TYK2, JAK1, JAK2, and JAK3, have been associated with diverse immune-related diseases and have now been implicated in COVID-19 severity and susceptibility." (PMID 40410684, 2025). "FXR/RXR, DPP4, JAK2, and ACE are associated with COVID-19, while CNGA1, BLT1, COX2, and 5-LOX are linked to pharyngitis." (PMID 40076279, 2025). "JAK2, which was identified as a hub gene, was supposed to be a potential therapeutic gene targets during the immunological process of COVID-19 and IS." (PMID 36969251, 2023). "Baricitinib is a selective JAK1/JAK2 inhibitor approved for the treatment of RA and has shown significant morbidity and mortality benefits in COVID-19." (PMID 36987476, 2023). "Recent investigations report an elevated expression of genes encoding IRF1, IRF5, IRF7, JAK2, and PML in severe COVID-19 patients." (PMID 38022551, 2023). "An in vitro study by Wu and Yang, (2020) suggested the promising potential of selective JAK2 inhibitor fedratinib in suppressing TH17-associated cytokine production (IL-17, IL-22, GM-CSF) during the management of COVID-19 and other related viruses." (PMID 37021053, 2023).
COVID-19 (continued). "Among these, the JAK2 inhibitors, Ruxolitinib and Tofacitinib, had been used to treat COVID-19 and cytokine release syndrome." (PMID 38143441, 2023). "The newly clinical trial results showed that Baricitnib, the JAK2 inhibitor, was synergistic with Remdesivir to improve the outcome of COVID-19 patients." (PMID 35676404, 2022). "Of note, the National Institutes of Health (NIH) have recently initiated drug combination clinical trials including Remdesivir plus dexamethasone or baricitinib (JAK2 inhibitor) for COVID-19 treatment." (PMID 35676404, 2022). "Together, these findings provide a rationale for the use of JAK2 inhibitors Fedratinib and Momelotinib to treat severe COVID-19 patients since they can attenuate calprotectin production in neutrophils." (PMID 36172386, 2022). "Oral activator (JAK2) and reduce the progression of acute respiratory distress syndrome and mechanical ventilation in hospitalized patients with COVID-19." (PMID 36111104, 2022). "Ruxolitinib, as a selective inhibitor of JAK1 and JAK2, is able to counteract hyperinflammation and is currently being investigated for use in treating COVID-19 infected patients." (PMID 35337171, 2022). "Consistent with this, recent studies have demonstrated efficacy for the JAK/JAK2 inhibitor Baricitinib in the treatment of COVID-19, a result that would have been anticipated by our data." (PMID 35421120, 2022). "Corticosteroids like dexamethasone, tocilizumab (IL-6 receptor blocker), and baricitinib (JAK 1 and JAK 2 inhibitor) are indicated in the management of patients with severe to critical COVID-19." (PMID 35698593, 2022). "Baricitinib, a selective inhibitor for JAK1 and JAK2 commonly used for rheumatoid arthritis, has shown in combination with an antiviral, known as remdesivir, to decrease recovery time for patients with COVID-19, particularly those on high flow oxygen." (PMID 34248990, 2021). "JAK1 and JAK2 inhibitors came out also as interesting candidates for repurposing, with several inhibitors being actively tested in COVID-19 patients." (PMID 34293006, 2021). "Fedratinib is a highly selective inhibitor of JAK2 and a modest inhibitor of JAK1 and JAK3 showed efficacy against cytokine storms caused by COVID-19 via the downregulation of T helper-17-associated cytokines." (PMID 34359931, 2021). "The oral JAK1/JAK2 inhibitor baricitinib has been intended to use as an anti-inflammatory or anti-cytokine agent in COVID-19 in a few setups across the world." (PMID 33962573, 2021). "Adaptive COVID-19 treatment trial-2 (ACCT-2) has tested the benefit of combining baricitinib (a specific inhibitor of Janus kinase-1 and Janus kinase-2) with remdesivir in critically ill patients of COVID-19." (PMID 34159203, 2021). "Baricitinib is a selective inhibitor of JAK1 and JAK2 and believed to interfere with the signaling of key cytokines that are produced abundantly in COVID-19, including IL-2, IL-6, IL-7, and granulocyte monocyte colony-stimulating factor." (PMID 34359931, 2021). "For example, the Jak1/Jak2 inhibitor ruxolitinib is currently under investigation in clinical trials in severe COVID-19 patients (NCT04338958; NCT04359290; NCT04348071)." (PMID 33324210, 2020). "Together, this would support proposed anti-IL-17 or JAK2 inhibitor therapies for severe COVID-19 disease." (PMID 33067472, 2020). "Wu and Yang, thus, proposed selective targeting of JAK2 inhibition to mitigate or even prevent the cytokine storm in COVID-19." (PMID 32707537, 2020). "Several authors suggest the use of JAK inhibitors (JAKi) in the treatment of COVID-19 as in the case of Baricitinib, a JAK inhibitor targeting JAK1 and JAK2, mechanistically able to inhibit the signaling of many COVID-19-related cytokines." (PMID 32973818, 2020). "Baricitinib, another Jak1/Jak2 inhibitor, is also under investigation for COVID-19 patients (NCT04340232)." (PMID 33324210, 2020).
COVID-19 (continued). "Of note in our case, we have three possible mechanisms that could explain the development of SCLS: COVID-19 vaccination, COVID-19 infection, and JAK2 V617F positivity." (PMID 39931582, 2025). "In mice immunized through the administration of recombinant SARS-CoV-2 spike protein antigens, the decline in anti-COVID-19 antibodies caused by OxS and SOD decreased upon virus re-exposure, and the activation of the JAK2/STAT1 pathway was efficiently counteracted by upregulating SOD production." (PMID 39768279, 2024). "We observed that COVID-derived PBMCs and monocytes showed significantly increased levels of receptor subunit Gp130, the receptor-associated kinase JAK2, STAT1, and STAT3, and the negative regulator SOCS3 (respectively) as a function of COVID-19 disease severity." (PMID 37310504, 2023). "Baricitinib blocks this pathway by inhibiting JAK-1 and JAK-2, thereby downregulating the inflammatory cytokine storm in COVID-19, and may have additional antiviral activity." (PMID 38050265, 2023). "Among five hub genes shared between two diseases, only JAK2 has drug target information, which might suggest that JAK2 could play important roles in the treatment of patients with COVID-19 accompanied with IS." (PMID 36969251, 2023). "Previous studies have also indicated that SYK and JAK2 may serve as target proteins related to COVID-19." (PMID 37037848, 2023). "Furthermore, results evidenced that COVID-19-positive patients with higher expressions of JAK2 and STAT1 showed increased MX1, MX2, ISG15, and OAS1 mRNA levels." (PMID 36298734, 2022). "In addition, a set of core signaling pathways, like PI3K, ERK1/2, NFkB, JAK-STAT, p38MAPK, JNK, were activated, which are the potential therapeutic targets, like JAK2, for identifying potentially effective COVID-19 treatments." (PMID 35676404, 2022). "Taken together, our data suggest that JAK2 inhibitors may be tested in COVID-19 patients with any of the comorbid conditions we investigated here with proper precaution." (PMID 34067609, 2021). "As ruxolitinib inhibits both JAK1 and JAK2, it may be a rather promising candidate to be used in COVID-19 induced hyperinflammatory diseases." (PMID 34385593, 2021). "The JAK2 inhibitor fedratinib has been reported to reduce mortality from COVID-19 and ruxolitinib (a tyrosine kinase inhibitor) inhibits viral infection by inhibition of JAK1 and JAK2 and other JAK inhibitors can block cytokine release associated with COVID-19-induced cytokine storm." (PMID 34067609, 2021). "Baricitinib, a JAK1/JAK2 inhibitor has been found to be effective in COVID-19 treatment." (PMID 33668085, 2021). "Moreover, DHODH, HDAC, and JAK2 are considered noteworthy targets in COVID-19-related research." (PMID 39130417, 2024). "Furthermore, JAK2/STAT3 signaling contributes greatly to the cytokine storm seen in severe COVID-19 via inducing the Th1/Th17 immune response, hyperactivating STAT3 while impairing STAT1 function, thereby suppressing the antivirus interferon response and coagulopathy." (PMID 39201692, 2024). "Importantly, nintedanib and ruxolitinib that target JAK2 may be used in COVID-19 cases having any of the five comorbid conditions." (PMID 34067609, 2021). "The results demonstrated that high doses of isochlorogenic acid C inhibited FXR/RXR, DPP4, JAK2, ACE, CNGA1, BLT1, COX-2, and 5-LOX, suggesting its potential to modulate COVID-19-related inflammatory pathways." (PMID 40076279, 2025). "The results showed that rutin exhibited a strong inhibitory effect on FXR/RXR, DPP4, JAK2, and ACE, suggesting its potential as a therapeutic agent for modulating these COVID-19-related targets." (PMID 40076279, 2025). "Three FDA-approved drugs for other indications were repurposed for COVID-19 treatment: Baricitinib, Ruxolitonib, and Tofacitinib, which target JAK1/JAK2, JAK1/JAK2, and JAK1/JAK3, respectively." (PMID 39599762, 2024).
COVID-19 (continued). "The differentiation of CD4+ T cells, activated by the interaction of IL-23 with TYK2/Jak2, occurs with the participation of IL-6, IL-1β and TGF-β, which is extremely important in the context of the cytokine storm in COVID-19." (PMID 37896870, 2023). "Ruxolitinib is a selective JAK1 and JAK2 inhibitor that also has modest selectivity against tyrosine kinase (TYK) 2 and JAK3 and shows benefit in COVID-19." (PMID 36987476, 2023). "Tocilizumab, a monoclonal anti-IL6 receptor antibody, and baracitinib, a monoclonal antibody that inhibits JAK1 and JAK2 (which are activated in response to IL6 signaling), have also demonstrated initial clinical efficacy in COVID-19 patients." (PMID 37090709, 2023). "Ruxolitinib, the third most-screened medicine, is known for inhibiting JAK1 and JAK2 and thereby inhibiting tumor invasion and tumorigenesis in human GBM, and it was also employed during COVID-19 for combined antiviral and anti-inflammatory therapy." (PMID 36834974, 2023). "A recent study using artificial intelligence techniques revealed that genes involved in activation of immune pathways (IL-6, TNF, JAK2, IL-1B, SERPINE1, TGFB1, CD8A, and VWF) serve as major hubs in the COVID-19- thrombocytopenia interactomes." (PMID 35372456, 2022). "Different JAK inhibitors have been proposed for the treatment of COVID-19, namely: JAK1/JAK2/TYK2 inhibitors (e.g., baricitinib, ruxolitinib), selective JAK2 inhibitors (e.g., fedratinib), and - more recently - JAK1/JAK3 inhibitors (e.g., tofacitinib)." (PMID 35340805, 2022). "In hospitalized patients with mild-to-moderate COVID-19, the combination of SOC with anti-IL-17A or anti-IL-6R therapy were superior or comparable to the combination with JAK1/JAK2 inhibitor, and all three were superior to SOC alone." (PMID 36001576, 2022). "Tofacitinib, which inhibit JAK1, JAK2, and JAK3, and baricitinib and ruxolitinib, both acting against JAK1 and JAK2 are currently under investigation for COVID-19." (PMID 34421600, 2021). "This predictive model assembling severe COVID-19-related proteins supports a role for known contributors to the cytokine storm such as IL1β, IL6, TNFα, JAK2, but also less prominent actors such as IL17, IL23 and C5a." (PMID 34293006, 2021). "Elevated serum of interferon (IFN)-γ has been found in patients ARDS in COVID-19, and it exerts multiple effects through the JAK1/JAK2 signaling resulting to the activation of a inflammatory factors downstream cascade." (PMID 33323549, 2020). "Other anti-inflammatory agents were also tested in their effectiveness by repurposed drugs for COVID-19 therapy and involved positive results under mediators such as inhibitors of C5, IL-1, JAK1, JAK2 and IL-33 and related to reducing release of TNF-α and IL-1β." (PMID 35843719, 2022). "In general, the use of ruxolitinib has been authorized in COVID-19 patients with respiratory insufficiency, and clinical evidence has suggested that this inhibitor of JAK1 and JAK2 can reduce inflammatory pulmonary reaction and potentially prevent the use of intensive care." (PMID 35337171, 2022). "Furthermore, the inflammatory response of COVID-19 exhibits a similar macrophage-derived cytokine profile as hemophagocytic lymphohistiocytosis, which is responsive to the selective JAK1/JAK2 inhibitor ruxolitinib." (PMID 36226977, 2022). "Inhibits JAK3, JAK1, JAK2, and to a lesser extent TYK2 and inhibits receptor signaling through pairs of JAK2 and because it can suppress the production of different cytokines, such as IL-2, IL-7 and IL-6 can used for patients with COVID-19." (PMID 36111104, 2022). "Blocking of TLR4, JAK2 and STAT3 signaling could prevent excessive production of calprotectin by Dok3-/- neutrophils, revealing new targets for potential COVID-19 therapy." (PMID 36172386, 2022). "Bioinformatics analyses showed upregulation of MAP2K6, CBL, RUNX3, STAT1, and JAK2 in COVID-19-positive vs. -negative patients." (PMID 36298734, 2022).
COVID-19 (continued). "Furthermore, JAK3, JAK2 and TYK2, which are highly activated in COVID-19, may be co-targeted with cytokine-modulatory therapy." (PMID 38389037, 2024). "JAK1 and JAK2, non-receptor tyrosine kinases involved in multiple stages of cell development and epigenetic modification processes, impact the inflammatory process and virus entry events in COVID-19." (PMID 39130417, 2024). "Results from extensive bioinformatics analyses in a case-control study from COVID-19-positive (n = 430) and -negative (n = 54) patients identified a signature of 13 dysregulated IFN-γ-associated genes, including STAT1 and JAK2, both key mediators of the IFN-γ signaling." (PMID 36298734, 2022). "Considering that fedratinib/pacitinib spare antigen-specific T-cell activity and minimize opportunistic infections, selective JAK2 inhibitors could be initially trialed rather than broader JAK1/2 inhibitors in the treatment of COVID-19 CRS." (PMID 36111104, 2022). "Furthermore, Ruxolitinib, a JAK1/JAK2 inhibitor acting downstream of JAK-dependent chemokines/cytokines such as IFN-γ, IL-1β, IL-6, TNF, G-CSF, CXCL9, and CXCL10, has shown promising results in treating COVID-19." (PMID 35269470, 2022). "However, our non-comparative results of severe COVID-19 patients showed that MSCs are not transcribing JAK2." (PMID 35095855, 2021). "Interestingly, although JAK2 and STAT1, two of the main genes involved in the IFN-γ canonical pathway, presented a positive and significant correlation for non-COVID19 (r = 0.390, p < 0.01), this correlation was significantly increased in COVID-19-positive patients (r = 0.82, p < 0.001) patients." (PMID 36298734, 2022). "Additionally, Fedratinib, a Janus kinase-2 inhibitor (JAK2 inhibitor), can prevent the generation of TH17-mediated cytokine storm; therefore may improve the clinical condition of severely affected COVID-19 patients." (PMID 34447458, 2021).